NCOA1 (nuclear receptor coactivator 1)
Diseases named in the same sentence as NCOA1 in open-access papers (continued):
Sharing a sentence is not in itself a finding about the gene and the disease.
Obesity (14 papers, 2012 to 2026). Accumulation of substantial excess body fat. "Fifteen rare heterozygous missense variants in NCOA1 were recently found in individuals with severe, early-onset obesity using the exome sequencing or targeted sequencing data on 2548 obese individuals." (PMID 32449767, 2020). "Numerous enzymes associated with H3K9me3, the mark associated with heterochromatin, including acetyltransferases (SRC‐1/Ncoa1), deacetylases (Hdac3), methyltransferases (Suv39 h1 and G9a/Ehmt2), and demethylases (Jhmdh2a/Kdm3a, Jmjd2c/Kdm4c), have been linked to fatty liver, diabetes, and obesity." (PMID 29484800, 2018). "Taken together, our data suggest that leptin doses mimicking hyperleptinemia in individuals with obesity were able to activate NCOA1, contributing to the activation and phosphorylation of the JAK2/STAT3 pathway." (PMID 41562922, 2026). "Seven publications reported outcomes of MBS in patients with obesity caused by rare variants in LEPR, MC4R, NCOA1, PCSK1, POMC, SH2B1, or SIM1." (PMID 40560452, 2025). "It has been reported that NCOA1 overexpression can be observed in a variety of pathological conditions, such as diabetes, obesity, and tumors." (PMID 37509133, 2023). "It has been reported that NCOA1 overexpression has been observed in a variety of pathological conditions, such as diabetes, obesity, and carcinogenesis." (PMID 37509133, 2023). "Our findings suggest that miR-4443 acts in a tumor-suppressive manner by down-regulating TRAF4 and NCOA1 downstream of MEK-C/EBP-mediated leptin and insulin signaling, and that insulin and/or leptin resistance (e.g. in obesity) may suppress this pathway and increase the risk of metastatic CRC." (PMID 27842582, 2016). "Indeed, elevated leptin levels, a surrogate of hyperleptinemia seen in individuals with obesity, markedly enhance the proliferation, migration, and EMT of BC cells through STAT3 activation and NCOA1 upregulation." (PMID 41562922, 2026). "The deletion of NCOA1 in POMC neurons attenuates their depolarization by leptin, decreases POMC expression, and increases food intake, which accelerates high-fat diet-induced obesity." (PMID 32449767, 2020).
breast tumors (9 papers, 2004 to 2021). "In addition, high NCOA1 expression concomitant with high micro-vessel density (MVD) in breast tumors has been associated with poor prognosis." (PMID 28264017, 2017). "Moreover, we found that higher NCOA1 protein in human breast tumors is also positively associated with higher densities of small blood vessels." (PMID 26287601, 2015). "Furthermore, we demonstrated that VEGFa expression in and secretion from breast tumor cells are positively associated with the manipulated NCOA1 expression levels, suggesting that NCOA1 tightly regulates VEGFa expression in these tumor cells." (PMID 26287601, 2015). "NCOA1 has been associated with HER2 expression, metastasis, disease recurrence and poor survival and overexpression in 19–29% of breast tumors." (PMID 33593445, 2021). "NCOA1 promotes angiogenesis in breast tumors by enhancing the transcription of VEGFa via HIFα and AP-1." (PMID 33167967, 2020). "NCOA1 is overexpressed in 19–29% of human breast tumors and its overexpression positively correlates with HER2 expression, lymph node metastasis, disease recurrence and poor survival." (PMID 28264017, 2017). "We found that MVD in breast tumors expressing higher NCOA1 protein is significantly higher than that in breast tumors expressing lower NCOA1 protein." (PMID 26287601, 2015). "This is consistent with the role of NCOA1 in upregulating VEGFa to stimulate angiogenesis in human breast tumors." (PMID 26287601, 2015). "About 45% (64/140) and 55% (76/140) of breast tumors exhibited high (immunoreactivity score ≥ 3) and low (immunoreactivity score < 3) NCOA1 immunoreactivity." (PMID 26287601, 2015). "NCOA1 is also overexpressed in 19–29% of human breast tumors and its overexpression positively correlates with HER2 expression, lymph node metastasis, disease recurrence and poor survival." (PMID 26287601, 2015). "In 140 human breast tumors, high NCOA1 protein correlates with high MVD and patients with both high NCOA1 and high MVD showed significantly shorter survival time." (PMID 26287601, 2015). "It is possible that breast tumor cells with different levels of Ncoa1 expression also have different requirements on MVD for growth." (PMID 26287601, 2015). "There are 4 literature support of genes HIF-1 and NCOA1 related to breast neoplasm." (PMID 18254968, 2008). "Moreover, NCOA1 could promote angiogenesis in breast tumors by simultaneously enhancing both HIF1α- and AP-1-mediated VEGF-a transcription." (PMID 28060733, 2017). "Similarly, breast tumors with high NCOA1 protein also showed poor prognosis." (PMID 26287601, 2015). "To validate this important role of NCOA1, we performed semi-quantitative immunohistochemistry (IHC) for NCOA1 in the tumor cells and CD34 in the vascular endothelial cells of small blood vessels in 140 human breast tumors." (PMID 26287601, 2015). "Furthermore, the changes of other Ncoa1 functions independent of its angiogenic function caused by the changed Ncoa1 expression levels may counter-regulate the growth effects of angiogenesis in breast tumors." (PMID 26287601, 2015). "Mechanistically, NCOA1 has been shown to up-regulate Twist1, ITGA5, CSF-1, SDF1 and CXCR4 expression, which are partially responsible for promoting metastasis through potentiating breast tumor cell epithelial-mesenchymal transition (EMT), migration, invasion and macrophage recruitment." (PMID 26287601, 2015).
prostate carcinoma (8 papers, 2014 to 2025). A carcinoma that arises from epithelial cells of the prostate gland. "The profound inhibition of NCoA1 by miR-22 is of particular interest as NCoA1 is a transcriptional co-activator regulating multiple oncogenic pathways associated with disease progression and metastasis formation in breast and prostate cancer." (PMID 26244872, 2015). "The plot was thickened with associations between the expression of NCOA1, NCOA3, and MED27, lymph node involvement, and the overexpression of several genes linked to advanced prostate cancer stages." (PMID 40900470, 2025). "NCOA1, as the androgen receptor (AR) coactivator, was found to be involved in prostate cancer progression, while NCOA1 knockdown induced a significant decrease in migration and invasion through the upregulation of protein kinase D1 (PRKD1)." (PMID 28060733, 2017). "■ NCOA1, NCOA3, MED27, and ESRRA are associated with advanced prostate cancer." (PMID 40900470, 2025). "Targeting NCOA3 via genistein reduces cell proliferation and suppresses the development of prostate cancer in transgenic rat models, although knockout of NCOA1 does not significantly alter prostate cancer initiation and progression." (PMID 37435460, 2022). "Similarly, for prostate cancer, KDM1A, BRD4, and PRMT1 were depleted in LNCaP cells as well as AR, FOXA1 and NCOA1, thus serving as positive controls." (PMID 35973998, 2022).
colon cancer (5 papers, 2016 to 2025). "Additionally, NR3C2 is regulated by NCOA1, and this intensified regulation activates the Wnt/β-catenin signaling pathway, enhancing the invasion of colon cancer cells." (PMID 40585960, 2025). "Previous studies have shown that LEP up-regulates miR-4443, thereby suppressing NCOA1 and TRAF4, and decreasing the invasiveness of human colon cancer cells." (PMID 37282602, 2023).
ependymoma (5 papers, 2021 to 2025). A WHO grade II, slow growing tumor of children and young adults, usually located intraventricularly. "Two RELA-like ependymomas harbored a gene fusion involving C11orf95 with breakpoints in exon 5 and the NCOA1 gene, breakpoints in exon 14 (case 4) or exon 15 (case 5)." (PMID 33481105, 2021).
colorectal cancer (4 papers, 2022 to 2025). A primary or metastatic malignant neoplasm that affects the colon or rectum. "The increased activity of NCOA1 (P = 6.07×10−157) contributes to colorectal cancer progression by enhancing Hedgehog signaling." (PMID 40585960, 2025). "Protein factors that could regulate transcription of SMAD4-213 via AnnoLnc2 predicted binding sites upstream of/overlapping TSS that are expressed in colorectal cancer are CDX2, CEBPB, ELF1, NCOA1, NCOR1, NCOR2 and TFAP4." (PMID 39132157, 2024). "Leptin and insulin treatment of colorectal cancer (CRC) cell line (HCT-116) can elevate the expression of miR-4443, which subsequently leads to down-regulation of nuclear receptor coactivator 1 (NCOA1) and TRAF4, and ultimately hinders the invasion and proliferation of HCT-116 cells." (PMID 36250718, 2022).
rhabdomyosarcoma (4 papers, 2019 to 2023). A rare aggressive malignant mesenchymal neoplasm arising from skeletal muscle. "PAX3 was the 5′ fusion partner in 29 cases with 3′ partners being FOXO1 fusions identified in alveolar rhabdomyosarcoma cases, MAML3 and NCOA1 fusions in two different biphenotypic sinonasal sarcoma cases." (PMID 34745213, 2021).
bladder cancer (3 papers, 2021 to 2023). "The increased expression of NCOA1 in bladder cancer patients is positively correlated with the tumor clinical stage, the pathological grade, and lymph node metastasis." (PMID 37509133, 2023).
hepatocellular carcinoma (3 papers, 2017 to 2024). A malignant tumor that arises from hepatocytes. "miR-105 was reported to serve as tumor-suppressive miRNAs in glioma by targeting SOX9 and SUZ12, as well as in hepatocellular carcinoma by targeting NCOA1." (PMID 29258605, 2017).
spindle cell rhabdomyosarcoma (3 papers, 2021 to 2022). An uncommon variant of rhabdomyosarcoma characterized by the presence of whorls of spindle cells forming a storiform pattern. "NCOA1 is a known fusion partner of PAX3 (PAX3-NCOA1) in ARMS and of TEAD1 (TEAD1-NCOA1) in spindle cell rhabdomyosarcoma." (PMID 36232302, 2022).
anaplastic ependymoma (2 papers, 2019 to 2021). Anaplastic ependymoma is a rare, malignant type of ependymoma that most often arises in the supratentorial region of the brain of children and young adults and that manifests with variable symptoms including headaches, nausea, vision impairment, memory loss and difficulty walking. "Fusions between C11orf95 and NCOA1, a steroid receptor, have been described in a C11orf95-RELA negative supratentorial anaplastic ependymoma, but their biological significance is unknown so far." (PMID 31480400, 2019).
depression (2 papers, 2017 to 2023). "Moreover, the increase of NCOA1 during pregnancy was diminished in depressed patients, which also suggests an association between depression and NCOA1." (PMID 37186582, 2023). "Interestingly, several of the genes proximal to these SNPs have previously been associated with depression, including nuclear receptor coactivator 1 (NCOA1), which is 40398 bp downstream of rs2584937." (PMID 37186582, 2023).
esophageal cancer (2 papers, 2021 to 2023). A primary or metastatic malignant neoplasm involving the esophagus. "NCOA1 (Nuclear receptor coactivator 1) is a hormone-dependent regulator of gene expression associated to different cancers, such as breast and esophageal carcinomas." (PMID 36745330, 2023).
lung carcinoma (2 papers, 2019 to 2021). "Accordingly, we speculated that the mechanisms of ADI on treating lung cancer were associated with the regulation of ESR1, NCOA1, RXRA, and RELA." (PMID 33506873, 2021).
multiple myeloma (2 papers, 2017 to 2019). "One example is the detection of NCOA1 (nuclear receptor coactivator 1) as a myeloma susceptibility gene in Han Chinese." (PMID 31139207, 2019).
osteoporosis (2 papers, 2012 to 2023). A condition of reduced bone mass, with decreased cortical thickness and a decrease in the number and size of the trabeculae of cancellous bone (but normal chemical composition), resulting in increased fracture incidence. "Since NCOA1 is known to modulate the estrogenic effect in bone, we further investigated the role of this SNP in osteoporosis by examining existing GWAS data." (PMID 23284279, 2012).
acute leukemia (1 paper, 2021). A clonal (malignant) hematopoietic disorder with an acute onset, affecting the bone marrow and the peripheral blood. "Fusion genes involving NCOA1/2 have been recurrently identified in several types of soft tissue tumors and acute leukemia." (PMID 33576087, 2021).
acute pancreatitis (1 paper, 2021). An acute inflammatory process that leads to necrosis of the pancreatic parenchyma. "In summary, using network pharmacology methods and molecular docking techniques, this study identified quercetin and other active components in Salvia miltiorrhiza to be effective against acute pancreatitis by targeting PTGS2, NCOA1, and other key genes." (PMID 34868345, 2021).
Alzheimer disease (1 paper, 2021). A progressive, neurodegenerative disease characterized by loss of function and death of nerve cells in several areas of the brain leading to loss of cognitive function such as memory and language. "Yet it is noteworthy that other steroid receptor coactivators such as NCOA1/SRC1 are known to be important, rate-limiting modulators of transcriptional cascades implicated in neurodevelopment and behaviour, including aspects of cognition in Alzheimer’s disease." (PMID 33340069, 2021).
Anxiety (1 paper, 2020). Intense feelings of nervousness, tension, or panic often arise in response to interpersonal stresses. "NCOA1-/- mice show reduced anxiety, impaired motor learning, and lower pain threshold in males." (PMID 32449767, 2020). "In addition to disrupted energy homeostasis, NCOA1-/- mice show reduced anxiety-like behaviors in males but not in females, compared with WT littermates." (PMID 32449767, 2020).
astroblastoma (1 paper, 2021). "It is interesting to note that in our series with detailed histological typing, none of the ZFTA:NCOA1/2 fusions showed any astroblastoma phenotype, which highlights the potential role of the ZFTA partner in the histological phenotype." (PMID 34389065, 2021).
Autoimmunity (1 paper, 2021). The occurrence of an immune reaction against the organism's own cells or tissues. "NCOA1 can regulate IL-17, participate in the acute inflammatory process of AP, and play an important role in autoimmunity." (PMID 34868345, 2021).
Ewing sarcoma (1 paper, 2024). A small round cell tumor that lacks morphologic, immunohistochemical, and electron microscopic evidence of neuroectodermal differentiation. "Of the priority candidates, 6 were found with enriched dependency in Ewing Sarcoma cell lines (AKT1, BARD1, HSP90AA1, NCOA1, SETDB1, SMAD4)." (PMID 38177639, 2024).
head and neck carcinoma (1 paper, 2017). A carcinoma that arises from the head and neck region. "Besides, NCOA1 expression was shown to have prognostic significance in advanced-stage head and neck carcinoma." (PMID 28060733, 2017).
head and neck squamous cell carcinoma (1 paper, 2022). A squamous cell carcinoma that arises from any of the following anatomic sites: lip and oral cavity, nasal cavity, paranasal sinuses, pharynx, larynx, and salivary glands. "Recent studies have reported that CKMT1 and NCOA1 are biomarkers for survival in head and neck squamous cell carcinoma." (PMID 35077462, 2022).
invasive breast carcinoma (1 paper, 2013). A carcinoma that infiltrates the breast parenchyma. "In addition, elevated expression of Ets1 and Ets2 identified in invasive breast cancers has been correlated with increased expression of the p160 nuclear receptor coactivators NCOA1 (SRC1) and NCOA3 (AIB/SRC3)." (PMID 23874775, 2013).
metastatic prostate carcinoma (1 paper, 2016). A carcinoma that arises from the prostate gland and has spread to other anatomic sites. "NCOA1 over expression in the metastatic prostate cancer occurs in primary tumors rather than the normal prostate." (PMID 27713912, 2016).
neuroblastoma (1 paper, 2019). Neuroblastoma (NB) is the most common solid, extracranial childhood tumor. "NCOA1/SRC1 has been associated with HIV genome transcription in human neuroblastoma cell line SHSY-5Y." (PMID 31578247, 2019).
osteosarcoma (1 paper, 2011). A usually aggressive malignant bone-forming mesenchymal neoplasm, predominantly affecting adolescents and young adults. "Kressler and colleagues also demonstrated that PPARGC1B indirectly co-activates tamoxifen-bound ERα, which cooperates with NCOA1 to enable tamoxifen agonism in kidney and osteosarcoma cell lines." (PMID 21269472, 2011).
sarcoma (1 paper, 2021). A usually aggressive malignant neoplasm of the soft tissue or bone. "However, whereas four ZFTA:NCOA1/2 with four zinc fingers corresponded to three classical ependymal histomorphologies and one PXA-like morphology, all three of our ZFTA:NCOA1/2 fusions with only one zinc finger corresponded to a sarcoma-like phenotype." (PMID 34389065, 2021).
ZIKV infection (1 paper, 2023). "A recent study found that ZIKV infection in hNPCs resulted in reduced levels of PPAR-γ mRNA ls and NCOA1, coactivators of both RXR and PPAR-γ nucellar receptors." (PMID 37376550, 2023).